RNU4-37P (RNA, U4 small nuclear 37, pseudogene)
Gene: Small nuclear RNA gene on chromosome 8 (112,148,742 to 112,148,825, reverse strand). Ensembl gene ENSG00000222146.
Homologues: Orthologues: chimpanzee U4 (98% identical), macaque U4 (95% identical), rabbit U4 (76% identical), rabbit U4 (75% identical), dog U4 (71% identical), rabbit U4 (71% identical), dog U4 (69% identical). Paralogues in human: RNU4-91P (75% identical), RNU4-33P (73% identical), RNU4-36P (73% identical), RNU4-53P (73% identical), RNU4-59P (73% identical), RNU4-39P (71% identical), RNU4-87P (71% identical), RNU4-24P (70% identical), RNU4-28P (70% identical), RNU4-29P (70% identical), RNU4-30P (70% identical), RNU4-5P (70% identical), and 82 more.